EGFR (epidermal growth factor receptor)
Diseases named in the same sentence as EGFR in open-access papers (continued):
Sharing a sentence is not in itself a finding about the gene and the disease.
non-small cell lung carcinoma (continued). "Osimertinib, a third-generation tyrosine kinase inhibitor (TKI), has demonstrated significant efficacy in treating non-small cell lung cancer (NSCLC) patients with epidermal growth factor receptor (EGFR) mutations." (PMID 38895622, 2024). "Osimertinib is a third-generation epidermal growth factor receptor (EGFR)-tyrosine kinase inhibitor that has become the first-line treatment for non-small cell lung cancer harboring EGFR mutations, with the potential risk of QT prolongation and heart failure." (PMID 39267801, 2024). "A 48-year-old woman without obvious environmental risk factors was diagnosed with metastatic urothelial carcinoma harboring a mutation in EGFR typical of driver mutations for non-small cell lung cancer." (PMID 39057170, 2024). "This other study involved pre-approval access to amivantamab in patients with metastatic non-small cell lung cancer with EGFR exon 20 insertion mutations who have failed platinum-based chemotherapy." (PMID 38910714, 2024). "Erlotinib and gefitinib, for example, have significantly expanded the therapeutic landscape by specifically targeting mutations of the epidermal growth factor receptor (EGFR) in non-small cell lung cancer (NSCLC)." (PMID 39337925, 2024). "Ongoing clinical studies are providing new treatment options for non-small cell lung cancer patients with EGFR ex20ins mutations and paving the way for future therapeutic possibilities." (PMID 38919530, 2024). "We further demonstrate that EGFR single point mutations found in Glioblastoma or non-small cell lung cancer, impact the constitutive activity of EGFR and response to tyrosine kinase inhibitor." (PMID 38429428, 2024). "In patients with advanced non-small cell lung cancer, serum ApoA1 levels are associated with the frequency of EGFR T790M mutations and treatment response to EGFR tyrosine kinase inhibitors." (PMID 38212711, 2024). "In summary, we report the first case of furmonertinib using in advanced non-small cell lung cancer (stage IVb) with an EGFR-KDD mutation." (PMID 38974236, 2024). "The primary aim of our study was to develop and validate a DLR model to predict EGFR mutation status in non-small-cell lung cancer (NSCLC) patients." (PMID 38539465, 2024). "Various tyrosine kinase inhibitors, in particular, have shown high response rates (58–85 %) in brain metastases among EGFR mutation-positive non-small cell lung cancer patients, in whom brain metastases are common." (PMID 39035033, 2024). "The examination of the driver gene mutation was performed in 45 patients with non-small cell lung cancer who had received the first-generation EGFR-TKIs, and 25 (55.6%) were positive for EGFR T790M mutation." (PMID 38803532, 2024). "Activating driver mutations of the epidermal growth factor receptor (EGFR) gene are present in approximately 15–30% of patients diagnosed with non-small cell lung cancer (NSCLC)." (PMID 38539415, 2024). "Non-small cell lung cancer (NSCLC) patients with EGFR mutation (EGFRm) and symptomatic BM receiving first-line osimertinib and aumolertinib from two medical centers were collected." (PMID 38369644, 2024). "The U.S. Food and Drug Administration (FDA) has approved Mobocertinib and Amivantamab for the treatment of late-stage or metastatic non-small cell lung cancer patients with EGFR ex20ins mutations." (PMID 38919530, 2024). "Erlotinib, a highly specific tyrosine kinase inhibitor that can reversibly inhibit epidermal growth factor receptor mutations, is mainly used for targeted therapy following the failure of chemotherapy for non-small-cell lung cancer (NSCLC)." (PMID 39767682, 2024). "Partial EGFR inhibitors such as osimertinib promote the interaction of the E3 ubiquitin ligase MARCH8 with and polyubiquitination of PD-L1 for degradation by the proteasome pathway by inhibiting EGFR in EGFR-mutated non-small cell lung cancer." (PMID 38826132, 2024).
non-small cell lung carcinoma (continued). "The mutation of EGFR is the major factor associated with non-small cell lung carcinoma (NSCLC), in addition to a frequent mutation of KRAS and fusion of anaplastic lymphoma kinase (ALK)." (PMID 39056802, 2024). "Third-generation EGFR inhibitors, like Osimertinib, used in EGFR-mutated non-small cell lung cancer, specifically targeting the mutated kinase domains, are ineffective in EGFR-amplified or EGFRvIII-mutated GBM." (PMID 39272879, 2024). "Resistance to epidermal growth factor receptor (EGFR)–tyrosine kinase inhibitors (TKIs) is a significant cause of treatment failure and cancer recurrence in non-small cell lung cancer (NSCLC)." (PMID 39090096, 2024). "Epidermal growth factor receptor-tyrosine kinase inhibitors (EGFR-TKIs) are currently the first-line standard of care for patients with non-small cell lung cancer (NSCLC) that harbor EGFR mutations." (PMID 38163979, 2024). "Secondly, Activating mutations in the epidermal growth factor receptor underlying responsiveness of non-small-cell lung cancer to gefitinib, written by LYNCH TJ." (PMID 39872524, 2024). "The combination of chemotherapy and targeted therapy has been validated in non-small-cell lung cancer (NSCLC) patients with EGFR mutations." (PMID 39199558, 2024). "ATLANTIC is a phase 2, open-label, single-arm trial that assessed the effect of durvalumab as a third-line or later treatment for advanced non-small cell lung cancer in patients with EGFR mutations or ALK rearrangements." (PMID 38758372, 2024). "EGFR mutation is a key genetic alteration in non-small cell lung cancer (NSCLC), with mutation rate as high as 30% among NSCLC patients and approximately 16% among those with advanced lung adenocarcinoma." (PMID 39308869, 2024). "Osimertinib, a EGFR tyrosine kinase inhibitor, is the standard treatment for non-small cell lung cancer patients with EGFR mutations." (PMID 39594421, 2024). "Other examples of biomarkers used in current therapies include epidermal growth factor receptor (EGFR) inhibitors for non-small cell lung cancer patients with EGFR mutations and PARP inhibitors in cancers with Breast Cancer Gene 1/2 (BRCA1/2) mutations." (PMID 39202397, 2024). "The synergistic treatment of elemene plus TKIs for EGFR-mutated advanced non-small-cell lung cancer has entered Phase IV clinical trials (NCT04401059)." (PMID 39164783, 2024). "Remarkably, ctDNA levels are not solely dictated by tumor volume but are also influenced by genetic factors, including mutations in genes such as EGFR or KRAS in non-small-cell lung cancer." (PMID 38396722, 2024). "In contrast, C-CBL has been identified as a significant proto-oncogene in various cancers and linked to the downregulation of PDK1 in EGFR wild-type non-small cell lung cancers, suggesting its potential role in immune responses." (PMID 38272982, 2024). "An ideal example of targeted therapy is how the mutation status of EGFR can inform the treatment of non-small-cell lung cancer, which commonly metastasizes to the spine." (PMID 39199573, 2024). "The irreversible epidermal growth factor receptor tyrosine kinase inhibitors (EGFR TKIs) afatinib and dacomitinib are approved for first-line treatment of EGFR mutation-positive non-small cell lung cancer (NSCLC)." (PMID 38373960, 2024). "The development of epidermal growth factor receptor (EGFR)-targeted tyrosine kinase inhibitors (TKIs) has resulted in significant improvements in the treatment outcomes of patients with non-small cell lung cancer (NSCLC) harboring EGFR mutations." (PMID 39252953, 2024). "Clinicopathological characteristics of 70 patients with non-small cell lung cancer (NSCLC) stratified according to EGFR mutational status using Pearson's chi-squared test." (PMID 37042869, 2023). "For instance, EGFR gene mutations can be observed in approximately 10%–20% in Western non-small-cell lung cancer (NSCLC) patients, but as high as 40%–50% in Asian population." (PMID 37767514, 2023).
non-small cell lung carcinoma (continued). "Epidermal growth factor receptor (EGFR) mutations are the most common targetable oncogenic driver mutation in metastatic non-small cell lung cancer (NSCLC)." (PMID 36864384, 2023). "For example, Tyrosine kinase inhibitors (TKIs) targeting sensitizing mutations in the epidermal growth factor receptor (EGFR) gene constitute a vital cornerstone of non-small cell lung cancer management." (PMID 37325647, 2023). "Epidermal Growth Factor Receptor (EGFR) mutation is a common biomarker and therapy target for Non-Small Cell Lung Cancer (NSCLC)." (PMID 37201304, 2023). "EGFR mutation-specific inhibitors have been developed and made significant contributions to controlling EGFR mutated non-small cell lung cancer." (PMID 36875137, 2023). "In Japan, the driver gene abnormalities in non-small cell carcinoma, which is the most common of the EGFR gene abnormalities, is reported as being due to a mutation found in 35% of patients with lung adenocarcinoma." (PMID 37280663, 2023). "Assessment of the quality and current performance of computed tomography (CT) radiomics-based models in predicting epidermal growth factor receptor (EGFR) mutation status in patients with non-small-cell lung carcinoma (NSCLC)." (PMID 37511192, 2023). "This study mainly observes the efficacy and safety of almonertinib plus chemotherapy compared with almonertinib alone in the second-line treatment of advanced non-small cell lung cancer (NSCLC) with mutated epidermal growth factor receptor (EGFR)." (PMID 37752994, 2023). "Combination of vascular endothelial growth factor (VEGF) inhibitors is an advantageous strategy in non-small-cell lung cancer patients with EGFR mutations." (PMID 38017514, 2023). "Epidermal growth factor receptor (EGFR) tyrosine kinase inhibitors (TKIs) represent the most common targeted drugs and play a crucial role in treating non-small cell lung cancer with EGFR gene mutations." (PMID 37251922, 2023). "Up to 60% of patients with non-small-cell lung cancer with epidermal growth factor receptor (EGFR) acquire a T790M mutation after first-line EGFR-tyrosine kinase inhibitors (TKIs)." (PMID 36900237, 2023). "Randomized phase three trial on patients with epidermal growth factor (EGFR) mutation stage II-IIIA non-small cell lung cancer (NSCLC) gave adjuvant Gefitinib (G) treatment versus vinorelbine plus cisplatin (VP) to assess overall survival (OS)." (PMID 36788891, 2023). "Studies have reported that concurrent EGFR/ALK co-mutation in non-small cell lung cancer patients is rare, with a prevalence ranging from 0.1% to 1.6%." (PMID 37705536, 2023). "Some of these so-called tyrosine kinase inhibitors (TKIs), like afatinib, erlotinib, gefitinib, and osimertinib, are already approved for treating patients with EGFR-mutated non-small-cell lung cancer." (PMID 37623256, 2023). "An increased level of GLS2 transcript and protein was detected in epidermal growth factor receptor (EGFR)-mutated non-small cell lung cancer (NSCLC) tissues compared to EGFR wild-type tumors." (PMID 38067269, 2023). "Epidermal growth factor receptor (EGFR) mutation is the most common oncogenic driver gene in advanced non-small cell lung cancer (NSCLC), accounting for approximately 50% of patients." (PMID 36894581, 2023). "Patients older than 60 years of age with EGFR amplification experienced a lower rate of VTE, contrary to some reports on non-small-cell lung cancer linking EGFR amplification to VTE risk." (PMID 37232831, 2023). "Clinical trials demonstrated that targeted therapy with epidermal growth factor receptor (EGFR) inhibitors improved progression-free survival and overall survival in patients with non-small cell lung cancer with EGFR mutations." (PMID 37371940, 2023). "Non-small-cell lung cancer (NSCLC) patients become resistant to targeted therapies such as tyrosine kinase inhibitors (TKIs) through mutations in the EGFR gene and by overexpression of proteins such as p120-catenin and PRMT-1." (PMID 37444572, 2023).
non-small cell lung carcinoma (continued). "It has been approved by both the food and drug administration and European Medicines Agency for the treatment of non-small cell lung cancer patients with locally advanced or metastatic EGFR-mutated tumors, including those who have acquired T790M mutations." (PMID 37653755, 2023). "Exosomes targeting EGFR-mutant non-small cell lung cancer were prepared by hydrophobic interaction between fluorophore/EGFR aptamer-linked cholesterol and lipid bilayer of exosomes, following the encapsulation of STAT3 siRNA." (PMID 37635253, 2023). "After these studies, both first- and second-generation TKIs were approved for first-line treatment of EGFR mutation-positive advanced non-small-cell lung cancer." (PMID 36900362, 2023). "A retrospective analysis of EGFR-TKIs and radiotherapy for advanced non-small cell lung cancer patients with EGFR mutations showed that the incidence of RP above grade 3 or even fatal RP was as high as 10%." (PMID 37287014, 2023). "Gefitinib, the first approved EGFR-TKI (EGFR—Tyrosine Kinase Inhibitors), was shown to be effective in treating non-small cell lung cancer (NSCLC) patients with EGFR mutations, leading to improved progression-free survival and response rates." (PMID 37760616, 2023). "To test this, we knockdown GRP78 by siRNA in a panel of 7 human non-small-cell lung carcinoma cell lines (NSCLCs) bearing different EGFR genotypes, including the commonly mutated and amplified EGFR alleles." (PMID 37487081, 2023). "Epidermal growth factor receptor-tyrosine kinase inhibitors (EGFR-TKIs) targeting EGFR are effective in EGFR mutation-positive non-small cell lung cancer (NSCLC) patients, but drug resistance is inevitable." (PMID 38061889, 2023). "In non-small cell lung cancer resistant to Osimertinib, Axl associates with EGFR and ErbB3, suggesting a prominent role of Axl and ErbB coexpression in the refractoriness to targeted therapy resistance." (PMID 37746265, 2023). "Non-small-cell lung cancer (NSCLC) is often driven by activating mutations in EGFR, i.e., p.L858R or the deletion of exon 19 (Ex19del)." (PMID 36986673, 2023). "Epidermal growth factor receptor tyrosine kinase inhibitors (EGFR-TKIs) are the first-line standard treatment for advanced non-small cell lung cancer (NSCLC) with EGFR mutation." (PMID 37649478, 2023). "The epidermal growth factor receptor (EGFR) is one of the most frequently mutated driver oncogenes in non-small cell lung cancer (NSCLC), and EGFR mutation is found in approximately 50% of the Southeast Asian lung adenocarcinoma population." (PMID 37649478, 2023). "Tyrosine-kinase inhibitors (TKIs) of epidermal growth factor receptor (EGFR) usually provide a potent anti-tumor efficacy with robust radiographic response for non-small cell lung cancer (NSCLC) harboring activating mutations in the EGFR gene." (PMID 39516993, 2023). "EGFR-TKIs have been used as a novel therapeutic strategy in patients with advanced non-small cell lung cancer (NSCLC) with EGFR mutations, significantly improving prognosis." (PMID 38074729, 2023). "In terms of in vitro diagnosis, the applications of Crispr detection in Zika virus and dengue virus detection, HPV screening in cervical cancer and detection of EGFR mutation in non-small cell lung cancer are becoming increasingly mature." (PMID 37029174, 2023). "The meta-analysis showed that non-small cell lung cancer patients with EGFR mutations had a higher odds of HPV infection." (PMID 37131310, 2023). "The clinical benefit of targeting EGFR in biliary tract malignancies has been less significant than other solid tumors with exceptional responses to these TKIs, such as EGFR-mutated non-small cell lung cancer." (PMID 38203714, 2023). "Previous studies have reported that PTEN mutations in breast cancer or EGFR mutations in non-small cell lung cancer metastatic tumors influence the metastatic pattern and further increase resistance to therapy." (PMID 37394583, 2023).
non-small cell lung carcinoma (continued). "IntroductionThe tyrosine-kinase inhibitor osimertinib is an oral anti-cancer agent that is used for the treatment of patients with metastatic non-small cell lung cancer harbouring sensitising EGFR mutations." (PMID 36942434, 2023). "The model was beneficial overall in detecting SNP variants consisting of large amounts of wildtype strands such as EGFR mutation genotyping for early detection of non-small cell lung cancer." (PMID 36658190, 2023). "Osimertinib has become the preferred first-line therapy for epidermal growth factor receptor (EGFR) mutation-positive metastatic non-small cell lung cancer (NSCLC) in recent years." (PMID 37887540, 2023). "Epidermal growth factor receptor (EGFR) sensitizing mutations were the most frequent driven alterations detected in non-small cell lung cancer (NSCLC), especially in Asian patients with lung adenocarcinoma." (PMID 37118803, 2023). "The EGFR L858R variant leads to poor prognosis and high incidence of malignant pleural effusion in non-small cell lung cancer, and the current small molecule drugs are only moderately effective against this variant." (PMID 36733714, 2023). "For example, we recently reported on the loss of KMT5C during the process of acquired resistance to EGFR inhibitors in EGFR mutant non-small cell lung cancer cell lines." (PMID 37671044, 2023). "The aim of the study was the modulation of the mutated epidermal growth factor receptor (EGFR) target, in the context of non-small-cell lung cancer, which presents acquired drug resistance." (PMID 36677894, 2023). "The clinical outcomes of sequential treatment of advanced epidermal growth factor receptor (EGFR)-mutated non-small cell lung cancer (NSCLC) patients with first-line bevacizumab combined with 1st/2nd-generation EGFR-TKIs are unclear." (PMID 37854677, 2023). "Previous studies have shown that mutations in EGFR (such as L858R/T790M or ex19Del) in non-small cell lung cancer (NSCLC) cell lines increase EGFR internalization and inhibit ligand-induced degradation." (PMID 38030597, 2023). "The updated results of the CHRYSALIS study found that following progression on platinum-based treatment, 114 patients with non-small cell lung cancer (NSCLC) with EGFR Exon 20 insertion mutations had a median OS of 23 months (95% CI 18.5–29.5)." (PMID 37895932, 2023). "We investigated the prevalence of genetic alterations and their association with epidermal growth factor receptor (EGFR) mutations and prognosis in early-stage non-small cell lung cancer (NSCLC) after curative resection." (PMID 38067382, 2023). "The management of non-small cell lung cancer with a common EGFR mutation has evolved over the past decades." (PMID 36765587, 2023). "Platinum-based chemotherapy is still the standard of care for Epidermal growth factor receptor (EGFR) mutated non-small cell lung cancer (NSCLC) patients after developing EGFR-TKI resistance." (PMID 37266427, 2023). "Conquering acquired resistance to osimertinib remains a major challenge in treating patients with epidermal growth factor receptor (EGFR) mutation-positive non-small-cell lung cancer (NSCLC)." (PMID 36597021, 2023). "We collected 326 H&E-stained non-small cell lung cancer slides from Beijing Chest Hospital, China, and used 226 slides (88 with EGFR mutations) for model training." (PMID 37407963, 2023). "We transfected the four destabilized (des) clones (desARE3’UTR ERBB2-1, desARE3’UTR ERBB2-2, desARE3’UTR ERBB2-3, desARE3’UTR ERBB2-4) and desARE3’UTR ERBB2-30 into non-small-cell lung cancer cells that carry mutation in the EGFR T790M but expresses ERBB2." (PMID 37359373, 2023).